MAP3K2 (mitogen-activated protein kinase kinase kinase 2)
Diseases named in the same sentence as MAP3K2 in open-access papers (continued):
Sharing a sentence is not in itself a finding about the gene and the disease.
Burkitt lymphoma (1 paper, 2015). A rare form of malignant mature B-cell non-Hodgkin lymphoma. "MiR-BART18-5p also controls the onset of replication in anti-Ig-treated Akata Burkitt’s lymphoma cell lines and in LCLs induced by TPA through its ability to target the expression of MAP3K2." (PMID 26694854, 2015). "MiR-BART18-5p was found to repress lytic replication in anti-Ig-treated Akata Burkitt’s lymphoma cell lines and in LCLs induced by TPA through its ability to target MAP3K2." (PMID 26694854, 2015).
cyst (1 paper, 2021). A sac-like closed membranous structure that may be empty or contain fluid or amorphous material. "Therefore, MAP3K2 might play a vital role in ovarian aging and cyst formation." (PMID 35052428, 2021).
papillary thyroid cancer (1 paper, 2021). "HOXA-AS2 regulated the HOXA-AS2/miR-520a-3p/homeobox D8 and mitogen-activated protein kinase kinase kinase 2 axis in non-small lung cancer 46, and the miR-15a-5p/homeobox A3 (HOXA3) axis in papillary thyroid cancer." (PMID 33754013, 2021).
psoriasis (1 paper, 2024). An autoimmune condition characterized by red, well-delineated plaques with silvery scales that are usually on the extensor surfaces and scalp. "We demonstrated a potential relationship between DUSP1 and miR-34a; DUSP4 and miR-34a, miR-382, and miR-3188; MAPK9 and miR-1275, MAP2K7 and mir-200-5p; MAP3K2 and mir-200-5p, which may be the subject of further research in the context of psoriasis." (PMID 38445655, 2024). "Nevertheless, we demonstrated a potential relationship between DUSP1 and miR-34a; DUSP4 and miR-34a, miR-382, and miR-3188; MAPK9 and miR-1275, MAP2K7 and mir-200-5p; MAP3K2 and mir-200-5p, which may be the subject of further research in the context of psoriasis." (PMID 38445655, 2024).
RASopathy (1 paper, 2017). Developmental syndromes caused by germline mutations (or in rare cases by somatic mosaicism) in genes that alter the Ras subfamily and mitogen-activated protein kinases that control signal transduction. "Primary RASopathy gene SPRED1 is a negative regulator of the pathway; MAP3K2 encodes MEK kinase 2; RAPGEF2 encodes a Ras activator thought to control developmental neuronal migration in the cortex and formation of the corpus callosum." (PMID 28076348, 2017).
thyroid cancer (1 paper, 2016). "In order to investigate the potential mechanism of miR-106a-RARB regulating the viability of thyroid cancer cells, 8505C-miR106a(−) cells with overexpression of MAP3K2 (MEKK2) were used." (PMID 27342319, 2016).
tuberculosis (1 paper, 2025). A chronic, recurrent infection caused by the bacterium Mycobacterium tuberculosis. "The “MAPK Signaling Pathway” includes genes like MAP3K2, PLA2G4A, and NFKB1, Lastly, the “Tuberculosis” pathway involves IFNGR2, ITGB2, and IL12B." (PMID 40621499, 2025).
cancer (44 papers, 2012 to 2025). A tumor composed of atypical neoplastic, often pleomorphic cells that invade other tissues. "The lysine methyltransferase SET and MYND domain 3 (SMYD3) methylates MAPK kinase kinase 2 (MAP3K2) in some cancers, causing enhanced activation of MAPK signaling." (PMID 37976356, 2023). "Studies have confirmed that MAP3K2 is involved in several cancer types and is closely relate to the risk of mortality." (PMID 30765768, 2019). "After NMI knockdown, the expression levels of MAPK signaling pathway members, including Raf1, MAPK11, MAP3K14 and MAP3K2, which are associated with cancer invasion and metastasis, were obviously decreased HCC-LM3." (PMID 28077802, 2017). "In conclusion, targeting MAP3K2 in KRAS-mutated cancer cell lines could affect cellular growth and viability, making it a potential SL pair for further in vitro and in vivo confirmation." (PMID 37863651, 2024). "Nonetheless, our findings portend that other Ras-dependent cancers with increased abundance of SMYD3 are also likely to maintain a feedback loop driving high SMYD levels dependent on persistent activation of MAP3K2/MEK/ERK signaling." (PMID 37976356, 2023). "In this context, overexpression of SMYD3 actively participates in cancer progression by synergizing with the RAS–ERK oncogenic pathway through MAP3K2 methylation." (PMID 35819319, 2022). "Methylation of MAP3K2 by SMYD3 has been implicated in Ras-driven tumorigenesis, which makes SMYD3 a potential target for cancer therapy." (PMID 34281237, 2021). "SMYD3-mediated methylation of MAP3K2 promoted the activation of the Ras/Raf/MEK/ERK signaling module in cancer cell lines." (PMID 32582175, 2020). "Previous studies have reported that MAP3K2 can promote cell proliferation in different types of cancer and that some miRNAs can suppress the tumor by targeting MAP3K2." (PMID 30602381, 2019). "MEKK2 (MAP3K2) is a cytoplasmic serine-threonine kinase involved in cancer growth and metastasis formation." (PMID 30423915, 2018). "In a different perspective, experts revealed that submicron silica particles (SM-SiO2s) suppressed growth in various cancer cells, including breast cancer, by regulating the XLOC_001659/miR-98-5p/MAP3K2 pathway, suggesting a broader spectrum of miR-98-5p’s anti-cancer effects." (PMID 38872210, 2024). "Moreover, the transcripts of the following notional cancer genes were significantly increased: Rbl1, Bcl2l11, Map3k2, Bcl6, Ppp1, Cdc42, and Ppp2." (PMID 38731901, 2024). "Interestingly, EC is the human cancer that showed the higher percentage of cases wherein ERK5, MEK5, MAP3K2 and MAP3K3 are mutated." (PMID 36123565, 2022). "Additionally, MAP3K2 is a protein kinase that is a member of the Ras family of oncogenes, well-known to be activated in a large proportion of cancers." (PMID 33637115, 2021). "Previous studies indicate that Smyd3 can regulate cancer‐associated phenotypes through its enzymatic activities including methylation of histones (such as H3K4, H4K5, and H2A.Z) and non‐histone proteins (such as VEGFR and MAP3K2)." (PMID 32779886, 2020). "MAP3K2 may be involved in the regulation of MAPK signaling pathway in cancer deterioration by KEGG analysis." (PMID 30765768, 2019). "Thus, inhibiting MAP3K2 in certain cancers may play a role in the treatment of cancer." (PMID 35432472, 2022). "Amongst the cancer-relevant microRNAs, miR-582-5p suppresses cell growth and tumorigenesis by inhibiting the expression of oncogenes, including AKT3, MAP3K2 and NOTCH1." (PMID 33670427, 2021). "Recently, SMYD3 was shown to methylate the MAP3K2 and the AKT kinase and affect the Ras-activated pathway in certain types of cancer." (PMID 34069776, 2021). "Second, SMYD3-mediated methylation of MAP3K2 at lysine 260 potentiates activation of the Ras/Raf/MEK/ERK signaling module and promotes the formation of Ras-driven carcinomas." (PMID 32007952, 2020).
cancer (continued). "miR-302a is an important regulator of tumor occurrence and deterioration, while MAP3K2 and PBX3 genes are involved in cancer cell proliferation and apoptosis." (PMID 30765768, 2019). "Some of the target genes were closely related to cancer development, such as CDH2, ZEB2, MAP3K2, and SLC24A4." (PMID 28298809, 2017). "Among the down-regulated genes with LTR-001 stands SMYD3, which encodes a lysine methyltransferase involved in the methylation of MAP3K2, increasing MAP kinase signaling and promoting the formation of Ras-driven carcinomas." (PMID 26510915, 2015). "Other histone (e.g. H4K5 and H4K20) and non-histone (VEGFR, human epidermal growth factor receptor 2 (HER2), mitogen-activated protein 3 kinase 2 (MAP3K2), estrogen receptor (ER) and others) substrates of SMYD3 have, however, been discovered since this finding, especially in relation to cancer (Ref." (PMID 39320855, 2024). "Genome-wide analysis showed that MAP3K2 can act as stress-activated protein kinase in MAPK signaling pathway and may be involved in the regulation of MAPK signaling pathway in cancer deterioration." (PMID 35432472, 2022). "Moreover, Smyd3 has the capacity to modify non‐histone proteins VEGFR and MAP3K2 to promote metastasis and Ras/Raf/MEK/ERK signaling in cancer development." (PMID 32779886, 2020). "In addition, GO analysis and KEGG analysis showed that MAP3K2 and PBX3 participated in cancer regulation." (PMID 30765768, 2019). "The miR-93 targets programmed cell death 1 ligand 2 (PDCD1LG2, also known as PD-L2), which is related to cancer immunotherapy, and G-protein coupled receptor 137C (GPR137C), and mitogen-activated protein kinase kinase kinase 2 (MAP3K2, also known as MEKK2) in the RAS-MAPK signaling." (PMID 30615673, 2019). "MAP3K2/MEKK2 directly phosphorylates and activates c-Jun/stress-activated protein kinases (JNKs) and I-kappa-B kinases (IKKs), and promotes motility and invasiveness in cancer cells, in part through control of focal adhesion stability." (PMID 26041885, 2015). "More recently, it was demonstrated that methylation of MAP3K2 by the cytosolic KMT SMYD3 promotes tumour formation through activation of the Ras-signalling pathway, establishing a role also for cytosolic lysine methylation in cancer." (PMID 26448330, 2015). "Indeed, it interacts with and methylates several non-histone proteins (e.g., VEGFR1, HSP90, H2A.Z.1, MAP3K2, AKT1, ER, HER2), through which it activates specific pathways involved in the survival and proliferation of cancer cells." (PMID 35495117, 2022). "However, since this discovery, other histone (H4K5 and H4K20, for example) and non-histone (VEGFR, HER2, MAP3K2, ER, and others) substrates of SMYD3 have been described, primarily in the context of cancer." (PMID 33637115, 2021).
tumor (30 papers, 2012 to 2025). "Mechanistically, this was the result of tumor EV-EGFR driven Mitogen-Activated Protein Kinase Kinase Kinase 2 (MEKK2) phosphorylation, inhibiting IRF3 dimerization and IFN production." (PMID 35320943, 2022). "The tumor suppressor genes, MAP3K2 and MAP2K4, were the direct targets, which were inhibited by the two miRNAs." (PMID 32850377, 2020). "As expected, compared with the adjacent non-tumor tissues, both the MAP3K2 and MAP2K4 expression levels showed a prominent decrease in 20 HCC tissues, with significantly negative correlations to miR-519a-2-5p and miR-512-3p." (PMID 32850377, 2020). "MiR-26a also regulates the expression of critical signaling genes such as PTEN, RB1 and MAP3K2/MEKK2, promotes tumor growth and inhibits JNK-dependent apoptosis in vivo." (PMID 30583549, 2018). "Moreover, LICN01871 silencing suppressed the expression of LINC01871 and MAP3K2 while upregulating miR‐873‐3p levels in tumor tissues." (PMID 40035259, 2025). "In the scatterplot, the log2 value of the ratio between tumor and matched normal tissues from the same patient seemed to show a negative correlation (R2 = 0.1408; p = 0.04492), suggesting a potential relationship between MAP3K2 and miR-372-3p." (PMID 35432472, 2022). "Previous studies demonstrated that MAP3K2 activation could promote various tumour cells invasion and metastasis." (PMID 33320435, 2021). "MAP3K2 gene can inhibit cell proliferation and promote cell senescence and tumor occurrence." (PMID 35052428, 2021). "Therefore, the relationship between miR-338-3p and MAP3K2/ERK may powerfully influence the tumor deterioration." (PMID 35929837, 2022). "Therefore, MAP3K2 is a potential therapeutic target in tumour." (PMID 33320435, 2021). "Consistent with the in vitro findings, animal experiments showed that LINC01871 knockdown downregulated MAP3K2 protein expression and suppressed the phosphorylation of ERK, JNK, and p38 in tumor‐bearing mice." (PMID 40035259, 2025). "MAP3K2, also called MEKK2, can regulate various tumour development‐related pathways, including β‐catenin, wnt, hedgehog." (PMID 33320435, 2021). "Tumor-suppressive miR-34c was often downregulated in various types of tumor cells and regulated EMT through direct binding with SOX9, SATB2, MAP3K2, and DANCR mRNA." (PMID 32252322, 2020). "Several reports have revealed that MAP3K2 and MAP2K4 in some tumor types showed tumor-suppressive effects, particularly on tumor invasion." (PMID 32850377, 2020). "MAP3K2 and MAP2K4, two members of the JNK axis, show a sequential function of upstream and downstream in tumor regulation." (PMID 32850377, 2020). "Tumour cells in the galectin-1-rich environments express genes important for tumour progression such as SPIN1, FUSIP1, TRIM23, PTPLAD1, MAP3K2." (PMID 30925774, 2019). "For example, the MAP3K2 protein, a key upstream kinase in the MAPK signaling pathway, can activate downstream MAP2Ks, participate in the cellular stress response and immune response, participate in tumor cell proliferation and regulate AR protein degradation." (PMID 40078537, 2025). "Conversely, down-regulation of MAP3K2 and MAP3K3 in CRC, as seen in GC, may lead to dysregulation of apoptosis, cell cycle control, and immune responses, contributing to tumor development and aggressiveness." (PMID 39901302, 2025). "In addition, as expected, Western blot demonstrated circPUM1 knockdown could repress N‐cadherin, vimentin, MAP3K2 protein expression and up‐regulate E‐cadherin protein expression, indicating that circPUM1 could promote the progress of EMT in HCC tumour." (PMID 33320435, 2021).
infection (4 papers, 2016 to 2025). The state of being infected such as from the introduction of a foreign agent such as serum, vaccine, antigenic substance or organism. "The results revealed that with increasing infection time, the expression of IKBKG, AKT1, CDC37, MAP3K2, and PKN2 decreased, whereas the expression of MAP3K7 and KRAS2 increased." (PMID 40078537, 2025). "In 3D4/21 cells, with increasing NS5A infection time, the protein expression of AKT1, IKBKG, CDC37, MAP3K2, and PKN2 decreased, whereas the protein expression of KRAS2 and MAP3K7 increased." (PMID 40078537, 2025). "With increasing infection time, the expression levels of IKBKG and KRAS2 increased, whereas the expression levels of MAP3K7, MAP3K2, AKT1, CDC37, and PKN2 decreased." (PMID 40078537, 2025).
inflammation (1 paper, 2022). Aberrant reaction of the microcirculation characterized by movement of fluid and leukocytes from the blood into extravascular tissues. "The mitogen-activated protein kinase 2 (MAP3K2) is necessary for the IL-18-Th1 mediated intestinal inflammation via the IL-18-MAP3K2-JNK axis." (PMID 36032110, 2022).
MAP3K2 also shares sentences with these, for which no sentence is quoted: prostate carcinoma (4 papers); Arthritis (2); Autoimmunity (2); cardiac hypertrophy (2); colorectal cancer (2); Hypertension (2); medulloblastoma (2); ovarian carcinoma (2); rheumatoid arthritis (2); adenocarcinoma (1); adenoma (1); asthma (1); benign neurofibromas (1); bladder cancer (1); cardiac disease (1); cardiomyopathy (1); cerebral cavernous malformation (1); cervical cancer (1); chronic myeloid leukaemia (1); colorectal adenoma (1); lymph node metastasis (1); lymphoma (1); metastatic disease (1); neurofibromatosis (1); neurofibromatosis type 1 (1); osteoarthritis (1); Osteopenia (1); pancreatic adenocarcinoma (1); pancreatic ductal adenocarcinoma (1); pulmonary fibrosis (1).
A further 4 diseases each share a sentence with MAP3K2 in 1 paper.